COL10A1 (collagen type X alpha 1 chain)
Description:
Type X collagen is a product of hypertrophic chondrocytes and has been localized to presumptive mineralization zones of hyaline cartilage.
Tractability: Antibody: its Gene Ontology location is reachable by antibodies, with high confidence; UniProt places it where antibodies can reach, with medium confidence; UniProt predicts a signal peptide or a membrane-spanning region.
Gene: Protein-coding gene on chromosome 6 (116,118,909 to 116,158,747, reverse strand). Ensembl gene ENSG00000123500.
Subcellular location: Secreted, extracellular space, extracellular matrix
Subcellular location (Human Protein Atlas): Endoplasmic reticulum; Predicted to be secreted
Pathways (Reactome):
Extracellular matrix organization: Assembly of collagen fibrils and other multimeric structures; Collagen biosynthesis and modifying enzymes; Collagen chain trimerization; Collagen degradation; Integrin cell surface interactions; Non-integrin membrane-ECM interactions
Gene Ontology:
Molecular function: extracellular matrix structural constituent conferring tensile strength; protein binding
Biological process: extracellular matrix organization; skeletal system development
Cellular component: collagen type X trimer; extracellular matrix; collagen trimer; endoplasmic reticulum lumen; extracellular region
Genetic constraint (gnomAD): Loss-of-function variants: 12 observed, 22.73 expected, observed/expected ratio (o/e) 0.53, 90% interval 0.34 to 0.86. The upper end of that interval is the gene's LOEUF score, 0.86, which puts it in group 3 of 6, group 1 being the genes least tolerant of losing a copy. Missense variants: 897 observed, 898.26 expected, observed/expected ratio (o/e) 1, 90% interval 0.94 to 1.05. Synonymous variants: 330 observed, 329.97 expected, observed/expected ratio (o/e) 1, 90% interval 0.91 to 1.1.
Gene-disease validity (ClinGen):
ClinGen rates the evidence that COL10A1 causes each of these diseases.
Schmid metaphyseal chondrodysplasia (autosomal dominant): Definitive. A rare skeletal disorder caused by a variation in COL10A1 gene and is characterized by moderately short stature with short limbs, coxa vara, bowlegs and an abnormal gait.
Homologues: Orthologues: chimpanzee COL10A1 (99% identical), macaque COL10A1 (98% identical), pig COL10A1 (88% identical), dog COL10A1 (86% identical), zebrafish col10a1a (54% identical), zebrafish col10a1b (52% identical). Paralogues in human: COL8A2 (52% identical), COL8A1 (51% identical), COL19A1 (37% identical), OTOL1 (23% identical), C1QTNF9 (20% identical), C1QTNF9B (19% identical), C1QTNF7 (16% identical), C1QTNF2 (16% identical), ADIPOQ (14% identical), C1QL2 (14% identical), C1QB (13% identical), C1QC (13% identical), and 11 more.
Diseases named in the same sentence as COL10A1 in open-access papers:
COL10A1 is named in the same sentence as 113 diseases in open-access papers, as found by Europe PMC text mining. Sharing a sentence is not in itself a finding about the gene and the disease. The quoted sentences say what the papers report.
breast carcinoma (39 papers, 2010 to 2026). "We subsequently assessed the set of INHBA-related genes in breast cancer and found that genes encoding collagens COL10A1, COL12A1, COL5A2 and COL11A1 were associated with INHBA expression." (PMID 41008625, 2025). "COL10A1 protein is a known extracellular matrix molecule released into the blood, and increased levels of circulating COL10A1 protein has been suggested as a diagnostic marker of breast cancer." (PMID 37287543, 2023). "To further study the underlying mechanism of COL10A1 in breast cancer, we conducted co-expression data mining of COL10A1 by the Oncomine database." (PMID 32043519, 2020). "It has been shown that upregulation of COL10A1 expression is significantly associated with the survival prognosis of breast cancer patients, and knockdown of COL10A1 significantly inhibits proliferation, migration, and invasion of breast cancer cells, as well as promotes apoptosis." (PMID 38063927, 2023). "Previous studies suggest that expression pattern of COL10A1 might act as a potential diagnostic predictor for early breast cancer." (PMID 37238942, 2023). "COL10A1, which encodes Collagen type X alpha 1, was found to be overexpressed in different types of cancer, such as esophageal cancer and breast cancer, and promoted the malignant progression by upregulating the expression of Prolyl 4-hydroxylase beta polypeptide (P4HB)." (PMID 35910202, 2022). "The data above indicated that COL10A1 could be associated with the LRRC15 signaling pathways in breast cancer." (PMID 32043519, 2020). "In addition, we identified COL10A1 as potential diagnostic biomarkers of luminal A breast cancer." (PMID 35692369, 2022). "COL10A1 protein levels in plasma might be a potential diagnostic predictor for early breast cancer." (PMID 32043519, 2020). "Through multi-omics integration, this study demonstrated that COL10A1+Fib are broadly enriched across nine prevalent solid tumor types, including lung, liver, gastric, and breast cancers." (PMID 40826474, 2025). "In breast cancer, elevated COL10A1 expression correlates with reduced tumor-infiltrating lymphocytes (TILs) and diminished immune cell infiltration, suggesting a potential role in shaping an immunosuppressive microenvironment." (PMID 40826474, 2025). "For instance, lncRNA HAGLROS sponges miR‐135b‐3p to block its degradation of COL10A1, resulting in COL10A1‐mediated STAT3 phosphorylation and activation of the IL‐10/STAT3 signaling loop that drives breast cancer‐associated M2 polarization." (PMID 41360672, 2025). "The highly upregulated gene COL10A1, promoting breast cancer progression and poor prognosis, and the consistently downregulated gene CDG300LG, linked to brain metastatic cancer, were identified." (PMID 40004168, 2025). "MTT, colony formation and EdU results showed that COL10A1 restored the proliferation ability of breast cancer cells suppressed by miR-135b-3p upregulation, and vice versa." (PMID 39198393, 2024). "LncRNA HAGLROS promotes proliferation, migration, invasion, EMT process and angiogenesis of breast cancer cells by targeting the miR-135b-3p/COL10A1 axis." (PMID 39198393, 2024). "Endothelial tube formation and VM results showed that COL10A1 restored the ability of miR-135b-3p upregulation-suppressed angiogenesis and luminal structure formation in HUVECs, HLECs and breast cancer cells, and vice versa." (PMID 39198393, 2024). "Our study confirmed that miR-135b-3p regulates the proliferation, migration, invasion, EMT process and angiogenic ability of breast cancer cells through COL10A1." (PMID 39198393, 2024). "Among the top 25 overexpressed genes in luminal-breast cancer, COL10A1 was the most highly elevated." (PMID 38806505, 2024). "Wound healing and Transwell results showed that COL10A1 restored the migration and invasive ability of breast cancer cells suppressed by miR-135b-3p upregulation, and vice versa." (PMID 39198393, 2024).
breast carcinoma (continued). "Recently, COL10A1 was identified as an overexpressed predictive biomarker for breast cancer coexpressed with LRRC15." (PMID 37287543, 2023). "Reports highlight that the expression of COL10A1 is markedly increased in colon, esophagus, and breast cancer and contributes to cell proliferation, migration, invasion and tumor vasculature." (PMID 37238942, 2023). "Again, our data that show up-regulation of COL10A1 gene in PP breast cancer samples are in line with previous published results in other pathologies." (PMID 36675137, 2023). "Previous work has demonstrated that COL10A1 expression was upregulated in a variety of tumor tissues, such as lung cancer, gastric cancer, and breast cancer." (PMID 38147021, 2023). "In this study, we identified 8 cDEGs (COL11A1, COL10A1, CD36, ACACB, CD24, PLK1, UBE2C, and PDK4) as breast cancer (BC)-causing HubGs from 3 microarrays and one scRNA-seq dataset by the protein-protein interaction (PPI) network analysis of 46 cDEGs." (PMID 37893423, 2023). "It has been reported that COL10A1 is highly expressed in most tumor tissues, such as breast cancer, colorectal cancer, and gastric cancer and so on." (PMID 36246404, 2022). "COL10A1 can exhibit specific expression in the vasculature and tumor microenvironment for breast cancer tissues via the immunofluorescence staining by using specific antibodies." (PMID 36276283, 2022). "By using GSE65194, we performed ROC curve analysis to access the diagnostic value of four DEmRNAs (TFF1, COL10A1, LEP, and PLIN1) and two DEmRNAs (PGM5-AS1 and TRHDE-AD1) in luminal A breast cancer." (PMID 35692369, 2022). "According to an analysis of breast cancer public databases, COL10A1 and PITX1 have been considered as predictive biomarkers for the prognosis of BC." (PMID 34895070, 2021). "Further experiments and clinical trials are essential to elucidate the value of COL10A1 in breast cancer treatment." (PMID 32043519, 2020). "To further investigate the role of COL10A1 in breast cancer prognosis, we verified that COL10A1 was positively correlated with metastatic RFS by the bc-GenExMiner software." (PMID 32043519, 2020). "GSEA analysis revealed the function of COL10A1 enriched in TGF-β signaling pathway in breast cancer." (PMID 32043519, 2020). "We further investigated the prognostic value of COL10A1 in breast cancer using the Kaplan–Meier Plotter, PrognoScan and bc-GenExMiner databases." (PMID 32043519, 2020). "The higher protein expression of COL10A1 was also detected in breast cancer tissues by UALCAN cancer database." (PMID 32043519, 2020). "The relationship between COL10A1 expression level and clinical indicators including prognostic data in breast cancer were analyzed by the Kaplan–Meier Plotter, PrognoScan, and Breast Cancer Gene-Expression Miner (bc-GenExMiner) databases." (PMID 32043519, 2020). "COL10A1 expression is elevated in many solid tumor types, such as colon cancer, esophagus cancer, and breast cancer, and displays vital roles in many critical cellular processes such as cell proliferation, migration, invasion and tumor vasculature." (PMID 32043519, 2020). "This is the first study to identify COL10A1 as a potential predictive biomarker for prognosis of breast cancer." (PMID 32043519, 2020). "In conclusion, this analysis revealed that COL10A1 was higher expressed in breast cancer compared with normal tissues and was correlated with a worse survival." (PMID 32043519, 2020). "The co-expression profile of COL10A1 was identified with a large cluster of 19139 genes across 66 breast carcinomas, and LRRC15 is a correlated gene." (PMID 32043519, 2020). "Genes with a high functional similarity to COL10A1 may be further investigated for a linkage to breast cancer." (PMID 40004168, 2025). "Importantly, the upregulation of COL10A1 has been demonstrated to promote breast cancer progression and lead to poor prognosis in patients." (PMID 40004168, 2025).
breast carcinoma (continued). "There is a number of scientific research for each of the top 10 mRNA genes, well-documenting their significance and association with cancerogenesis: ADAMTS5, TMEM220, ARHGAP20, MICU3; or precisely with breast cancer: COL10A1, MMP11, CAVIN2 (formerly known as SDPR), PLPP3, MME, and CD300LG." (PMID 40724805, 2025). "Increased expression of stromal ColX has previously been shown to correlate with worse survival outcomes in breast cancer cohorts with diverse tumor mutational burdens, and COL10A1 has also been linked to negative prognosis in pancreatic cancer." (PMID 39939916, 2025). "For example, COL10A1 is a well-established biomarker for breast cancer." (PMID 40004168, 2025). "To investigate the molecular mechanism of lncRNA HAGLROS/miR-135b-3p regulating the malignant progression of breast cancer, we screened the target gene COL10A1 of miR-135b-3p by database prediction and confirmed the binding potential of miR-135b-3p to COL10A1 by relevant assays." (PMID 39198393, 2024). "To elucidate whether the interaction between miR-135b-3p with COL10A1 can regulate the malignant evolution of breast cancer, we performed rescue experiments to examine the effect of COL10A1 in miR-135b-3p differentially expressing cells." (PMID 39198393, 2024). "Therefore, COL10A1 was selected as the target gene of miR-135b-3p, and the expression of COL10A1 was significantly higher in breast cancer cell lines than in breast epithelial cells." (PMID 39198393, 2024). "Previous bioinformatics analysis has demonstrated that COL5A2, COL10A1, and COL11A1 may be used as a diagnostic or prognostic biomarker for tumors such as gastric cancer, breast carcinoma, and non-small-cell lung cancer." (PMID 37082197, 2023). "In addition, it has been mentioned that in breast cancer, COL10A1 promotes cell proliferation, migration, and invasion by targeting prolyl 4-hydroxylase β polypeptide (P4HB)." (PMID 38063927, 2023). "Breast cancer patients may present less improvement due to the neoadjuvant chemotherapy relative to patients possessing high COL10A1 expression." (PMID 36276283, 2022). "Notably, the combination of COL11A1, COMP, and COL10A1 was identified as a promising biomarker to differentiate breast cancer patients from the benign controls." (PMID 33435254, 2021). "Although COL10A1 was reported to be highly expressed in tumors by high throughput sequencing, the specific role of COL10A1 in breast cancer was unknown." (PMID 32043519, 2020). "While breast cancer patients with up-regulated COL10A1 demonstrated worse RFS." (PMID 32043519, 2020). "COL10A1 could be considered as a predictive biomarker for prognosis of breast cancer with co-expressed LRRC15." (PMID 32043519, 2020). "COL10A1, as a member of the collagen family, was verified to be enrichment in the tumor, and many previous reports have revealed that COL10A1 was upregulated in gastric cancer, and breast cancer." (PMID 33324550, 2020). "The mRNA expression of COL10A1 in breast cancer was analyzed using the Oncomine database." (PMID 32043519, 2020). "Therefore, in the present study, we evaluated the significance of COL10A1 gene expression in breast cancer by using comprehensive bioinformatics analysis of the clinical indicators and survival data in several large online databases." (PMID 32043519, 2020). "Breast cancer patients with more advanced SBR grade tended to express lower COL10A1 gene." (PMID 32043519, 2020). "COL11A1 and COL10A1 have recently been proposed as markers to discriminate between breast cancer and healthy tissues and could be helpful in the diagnosis of suspicious breast nodules." (PMID 30835723, 2019). "COL10A1 has been included in stromal expression signatures in breast cancer." (PMID 27090210, 2016). "Therefore, circulating COL11A1, COMP, and COL10A1 could be used as biomarkers to diagnose breast cancer." (PMID 33435254, 2021).
breast carcinoma (continued). "Additionally, the concentration of COL10A1 in the plasma could be a potential biomarker to discriminate breast cancer patients from those with benign disease." (PMID 32043519, 2020). "For instance, lncRNA CASC15 sustains breast cancer stemness through the miR-654-5p/MEF2D axis, while HAGLROS promotes tumor evolution via the miR-135b-3p/COL10A1 pathway and exosome-mediated macrophage polarization." (PMID 41614739, 2025). "While every subtype has differential expression of COL10A1 and CDG300LG, each subtype has some unique genes that are differentially expressed but still have some significance to breast cancer." (PMID 40004168, 2025). "The genes namely COL11A1, MMP11 and COL10A1 were found up-regulated and PCOLCE2, LAMA2, TMTC1, and TIMP4 were found down-regulated in breast cancer cell lines also." (PMID 37238942, 2023). "In particular, COL10A1 serves as a poor prognostic marker in bladder cancer (OS and DSS), brain cancer (OS), breast cancer (RFS and DFS), colorectal cancer (OS, DSS, and DFS), lung cancer (OS and RFS), ovarian cancer (OS and DFS) and soft tissue cancer (DFS)." (PMID 38147021, 2023). "Among these key genes COL11A1, MMP11 and COL10A1 were highly expressed and PCOLCE2, LAMA2, TMTC1, ADAMTS5, TIMP4, and RSPO3 were having lower expression levels in breast cancer samples." (PMID 37238942, 2023). "In conclusion, our study identified nine key regulators, of which COL11A1, MMP11 and COL10A1 were up regulated and PCOLCE2, LAMA2, TMTC1, ADAMTS5, TIMP4 and RSPO3 were down regulated in breast cancer samples as compared to control samples." (PMID 37238942, 2023). "The genes namely COL11A1, MMP11 and COL10A1 were found up regulated and PCOLCE2, LAMA2, TMTC1, ADAMTS5, TIMP4 and RSPO3 were found down regulated in breast cancer." (PMID 37238942, 2023). "The protein expression results of TUBB3, MCM2, MYOC, FN1, S100A7, and TFF1 were consistent with the mRNA expression result COL10A1, LEP, PLIN1, PGM5-AS1, and TRHDE-AD1 were capable of discriminating luminal A breast cancer and normal controls." (PMID 35692369, 2022). "The results indicated that except for TFF1 (AUC = 0.774), COL10A1 (AUC = 1.000), LEP (AUC = 0.984), PLIN1 (AUC = 0.966), PGM5-AS1 (AUC = 0.969), and TRHDE-AD1 (AUC = 1.000) were capable of discriminating luminal A breast cancer and normal controls." (PMID 35692369, 2022). "COL10A1 and COL11A1, as members of the collagen family, are upregulated in breast cancer fibroblasts." (PMID 35505821, 2022). "COL10A1, LEP, PLIN1, PGM5-AS1, and TRHDE-AD1 were capable of discriminating luminal A breast cancer and normal controls." (PMID 35692369, 2022). "However, the prognostic value of COL10A1 in breast cancer remains unclear." (PMID 32043519, 2020). "Our study is the first to reveal the potential function between COL10A1 and TGF-β signaling pathway in breast cancer." (PMID 32043519, 2020). "However, the significance of COL10A1 expression in the prognosis of breast cancer remains unclear." (PMID 32043519, 2020). "Up-regulated expression of COL10A1, MMP11, CST1, GJB2, MMP1, MMP13, and CEACAM6; down-regulated expression of ADH1B, CIDEC, THRSP, GPD1, TIMP4, FABP4, and SCARA5 genes was common in breast cancers of the two populations." (PMID 31292488, 2019). "We also identified different collagen proteins (such as COL10A1 and COL11A1) that are up-regulated in luminal versus normal breast cancer samples." (PMID 30835723, 2019). "Up-regulated genes, such as COL10A1, MMP11, NEK2, PAFAH1B3, KIF4A are highly related to breast cancer." (PMID 28245581, 2017). "In addition, meta-analysis of breast cancer gene expression data has suggested that COL10A1 might be a predictive biomarker for prognosis of breast cancer, although the exact role of increased COL10A1 expression in breast tumor progression is currently unknown." (PMID 36940196, 2023). "Breast cancer patients with positive nodal status (N) showed increased level of COL10A1 than those with negative nodal status." (PMID 32043519, 2020).